INS (insulin)
Diseases named in the same sentence as INS in open-access papers (continued):
Sharing a sentence is not in itself a finding about the gene and the disease.
atherosclerosis (continued). "TCF7L2 is a downstream transcription factor in the canonical Wnt/β-catenin pathway, and it has been shown to be involved in insulin synthesis, vascular cell proliferation, inflammation, and plaque formation, all of which are key processes in atherosclerosis 39,58." (PMID 40303486, 2025). "Increased expression of CDKN1B is associated with structural and functional changes in the kidneys in diabetic nephropathy, decreased pancreatic β-cell proliferation and serum insulin levels, as well as decreased macrophage proliferation and inflammation in atherosclerosis." (PMID 39273245, 2024). "Finally, insulin therapy has also been shown to impact carotid intima-media thickness, a surrogate marker for atherosclerosis." (PMID 39125938, 2024). "NAMPT is the gene encoding visfatin, a dual-form ubiquitously expressed, whose functionality encompasses multiple processes related to insulin sensitivity, NDDs, lipid metabolism, atherosclerosis, and pro-inflammatory effects, including NLRP3 inflammasome activation." (PMID 39339745, 2024). "Studies have shown that insulin administration reduces the size of aortic atherosclerotic lesions in genetically modified mice, such as apolipoprotein E (ApoE) knockout mice, which are prone to atherosclerosis." (PMID 39125938, 2024). "Nevertheless, certain non-insulin medications, such as metformin, exhibit the ability to impede the progression of arterial thickening and exert a certain impact on the development of atherosclerosis." (PMID 39398332, 2024). "Insulin is believed to have a protective effect against the development of atherosclerosis." (PMID 39329916, 2024). "Adiponectin is a member of the adipokine family, which is secreted from adiposetissue, which is considered an endocrine organ, has antidiabetic andanti-inflammatory properties, and has functions such as insulin sensitivity,atherosclerosis, cell proliferation, and regulation of energy metabolism." (PMID 38655997, 2024). "Other possible reason is owing to enhance insulin sensitivity, improve systemic inflammation, and reduce platelet aggregation by low-to-moderate alcohol consumption, which may also be beneficial to atherosclerosis." (PMID 39496440, 2024). "Moreover, the KEGG enrichment analysis showed that FA mainly functioned in ROS, the HIF-1 signaling pathway, lipids and atherosclerosis, insulin resistance, and the PI3K-Akt signaling pathway." (PMID 39064719, 2024). "In addition, FOXO3 integrates the pleiotropic actions of insulin to protect the vascular endothelium from atherosclerosis." (PMID 39497655, 2024). "First, the sustained reduction in HbA1c and insulin resistance may benefit the vascular endothelium, microcirculation and reduce atherosclerosis progression." (PMID 38233592, 2024). "In other words, the original role of insulin in the endothelial cells, which is to counteract atherosclerosis, becomes impaired under conditions of IR, potentially accelerating the progression of atherosclerosis." (PMID 38572476, 2024). "IR can interfere with insulin signaling, enhance chronic systemic inflammation, reduce insulin sensitivity, and increase foam cell formation, thereby accelerating the formation of atherosclerosis and advanced plaques." (PMID 36609319, 2023). "Our results may be due to MASLD and atherosclerosis having common pathogenesis, including endothelial dysfunction, systemic inflammation, hepatic insulin resistance, increased oxidative stress, and changes in lipid metabolism." (PMID 37951879, 2023). "Therefore, further exploration of the regulatory effects of C-peptide, insulin, and the high-glucose environment on atherosclerosis is of significant importance." (PMID 37745697, 2023). "For example, PIK3R1 gene has 12 pathways, such as insulin resistance, relaxin signaling pathway, signaling pathway regulating stem cell pluripotency, fluid shear stress and atherosclerosis, AGE-RAGE signaling pathway in diabetic complication, focal adhesion, and so on." (PMID 36688087, 2023).
atherosclerosis (continued). "A LCHF diet may be beneficial, as it reduces glucose and insulin spikes, improves insulin sensitivity, and decreases the chances of developing atherosclerosis." (PMID 37626767, 2023). "To provide further insight into the question of whether DIAPH1-dependent roles in atherosclerosis were mediated through regulation of lipid vs. glucose/carbohydrate or insulin metabolism, we performed a series of correlation analyses." (PMID 36932214, 2023). "However, changes in metabolism such as, DEPs enriched in KEGG pathways of lipid and atherosclerosis, sphingolipid signaling, insulin signaling, and glycogen signaling seem to be more predisposed in the CIA + Dgal model." (PMID 36709303, 2023). "In an insulin-resistant and hyperglycemic environment, oxidized or glycated lipoproteins trigger a heightened inflammatory response beneath the endothelium, ultimately exacerbating atherosclerosis and increasing plaque instability." (PMID 37375712, 2023). "These factors are closely associated with the damage and dysregulation of vascular endothelial cell, inflammatory reactions in adipose tissues, insulin resistance, synthesis and secretion of pro-inflammatory cytokines, reactive oxygen species stress, and atherosclerosis." (PMID 35282431, 2022). "While testosterone was previously reported to improve insulin sensitivity, lower visceral adiposity and exert vasodilatory effects, clinical and animal research on the role of testosterone in atherosclerosis and related cardiovascular health remains inconclusive and rather contradictory." (PMID 36505365, 2022). "Recent tissue-selective deletion of Ide, in β-pancreatic cells, liver cells or bone marrow in mice has allowed the role(s) of IDE in metabolic phenotypes like β-cell function, insulin resistance, glucose tolerance, insulin clearance or atherosclerosis to be refined." (PMID 35406791, 2022). "PPARs, a kind of transcriptional factors belonging to nuclear receptor superfamily, are made up of PPAR‐a, PPAR‐b/d, and PPAR‐g, which are associated with adipocyte differentiation, lipid metabolism, hyperlipidemia, insulin sensitization, cancer, inflammation, and atherosclerosis." (PMID 35037412, 2022). "Insulin, nivolumab, indomethacin, and α-mangostin were predicted to be potential therapeutic agents for unstable plaques, some of which have been proven to have clinical benefits for atherosclerosis or ischemic stroke." (PMID 36211422, 2022). "Importantly, it regulates the onset and development of inflammation and metabolism, resists the progression of atherosclerosis, and improves insulin sensitivity." (PMID 36760798, 2022). "An ARIC study on the risk of atherosclerosis in the community found that for every 50 pmol/L increase in fasting insulin of nondiabetic patients, the relative risk (RR) of ischemic stroke will increase." (PMID 35242879, 2022). "This hypothesis is congruent with the beneficial effects of HDL against atherosclerosis as well as with their capacity to induce insulin secretion and merits experimental exploration." (PMID 35625916, 2022). "First, previous studies showed that glucosamine may increase fasting blood glucose, accelerate atherosclerosis, and reduce insulin sensitivity, which have been widely identified as risk factors for cardiovascular diseases." (PMID 36145069, 2022). "It has been found that chemicals produced by cooking meat at high temperatures (grilling/barbecuing) can induce inflammation, oxidative stress, and insulin resistance, and consequently lead to damage of the inner vascular wall and development of atherosclerosis." (PMID 36274164, 2022). "The risk factors for MS are closely associated with the progression of atherosclerosis, with cytokine secretion from adipocytes exerting a negative effect on insulin sensitivity, thereby resulting in endothelial dysfunction." (PMID 36295873, 2022).
atherosclerosis (continued). "However, the question on the role of insulin resistance of epicardial fat adipocytes in the development of atherosclerosis remains poorly understood." (PMID 33440802, 2021). "AKT S473 phosphorylation following insulin stimulation was associated with less amyloid angiopathy severity, but not with other vessel pathology including atherosclerosis and arteriolosclerosis." (PMID 33858515, 2021). "No other association of brain insulin signaling measures with vessel pathology, including atherosclerosis and arteriolosclerosis, was found." (PMID 33858515, 2021). "Since adiponectin increases cellular sensitivity to insulin and also possesses anti-atherogenic effects, a marked reduction in the circulatory concentrations of adiponectin results in IR and atherosclerosis via systemic inflammation." (PMID 33639960, 2021). "Mechanisms of obesity-induced atherosclerosis may involve insulin resistance, an imbalance of adipokines, oxidative stress, inflammation and endothelial dysfunction." (PMID 33937238, 2021). "In this regard, they explained that irisin may indirectly participate in the formation of atherosclerosis through fat or insulin." (PMID 34276559, 2021). "Overexpression of T-cadherin in endothelial cells attenuated insulin-induced PI3K/Akt/mTOR pathway activation and simultaneously reduced insulin-stimulated eNOS activation, migration, and angiogenesis, suggesting the role of endothelial dysfunction induced by T-cadherin in atherosclerosis." (PMID 33767629, 2021). "At the cellular level, impaired insulin signaling may interfere with the normal function of vascular intimal cells that are involved in atherosclerosis, including macrophages, endothelial cells and vascular smooth muscle cells." (PMID 33456363, 2021). "Interestingly, BMP2 also regulates a set of genes enriched in FoxO signaling, insulin resistance, and fluid shear stress and atherosclerosis, suggesting potential links to trophoblast metabolic regulation and trophoblast-endothelial cell remodelling." (PMID 34970543, 2021). "Normal insulin signaling in the vascular endothelium can protect against atherosclerosis." (PMID 34970228, 2021). "We did not observe any other association between the insulin signaling measures (including AKT phosphorylation by ELISA) with vessel pathologies such as atherosclerosis and arteriolosclerosis." (PMID 33858515, 2021). "Although the chosen primary revascularization method did not correlate with mortality, extensive atherosclerosis was associated with mortality both insulin and non-insulin diabetic." (PMID 33225841, 2021). "Extensive tibial atherosclerosis was an independent risk factor for limb loss and in both insulin- and non-insulin-treated diabetics, it was associated with increased mortality." (PMID 33225841, 2021). "Insulin promotes the surface expression of Mac-1 through the PI3K/Akt signaling pathway and promotes monocyte adhesion to and subsequent migration across endothelial cells, which is a key process in atherosclerosis-associated chronic inflammation." (PMID 33767629, 2021). "The signaling pathways were further integrated as network manner, including AGE-RAGE signaling pathway in diabetic complications, Fluid shear stress and atherosclerosis, Insulin resistance, HIF-1 signaling pathway, Th17 cell differentiation and IL-17 signaling pathway." (PMID 32863886, 2020). "In this sense psycho-emotional stress prepares the organism to the impact of “expected” extreme factor in near future, and in cases of “false alarms”, the excess of glucose needs to be utilized by the activation of insulin signaling contributing to pathologic continuum that leads to atherosclerosis." (PMID 32033390, 2020).
atherosclerosis (continued). "This nutrigenomic study identified changes in the expression of genes involved in processes such as cell adhesion and cell–matrix interactions; chemokine signaling; insulin secretion; calcium and potassium transport; as well as inflammation, atherosclerosis development, and neurostimulation." (PMID 32316129, 2020). "In the current study, we detected an effect of Nod1/2-deficiency on experimental atherosclerosis and lipid metabolism, whereas we did not observe effects on insulin resistance." (PMID 32588196, 2020). "In particular, oxidized low-density lipoprotein (oxLDL) regulates the expression of dipeptidyl dipeptidase IV (DPP4) in macrophages leading to the increase of CD36 + cells which are representative of the inflammatory processes of atherosclerosis in obese and insulin resistant patients." (PMID 33414766, 2020). "Adiponectin is an anti-inflammatory adipokine that may play important roles in the regulation of metabolism, insulin sensitivity, inflammation, and atherosclerosis." (PMID 32590951, 2020). "DHEA-S treatment may reduce lipogenesis and weight gain in rats, delay atherosclerosis in rabbits, increase insulin secretion and sensitivity in rats, and it may reduce cardiac fibrosis in diabetic rats." (PMID 32477267, 2020). "In addition, the administration of purified SELENOP was suggested to impair insulin signaling and disturb glucose metabolism, as well as play a role in the development of atherosclerosis." (PMID 32377302, 2020). "However, it seems that only disrupted levels of serum insulin, low and high insulin levels, link serum insulin with atherosclerosis." (PMID 31958313, 2020). "Twice-daily exenatide could prevent atherosclerosis progression in patients with T2DM over a 52-week treatment period compared with insulin therapy." (PMID 32334592, 2020). "Recent studies have demonstrated that impaired insulin signaling accelerates atherosclerosis." (PMID 32020855, 2020). "In contrast to high or low serum insulin levels, it may be speculated that physiological concentration levels (median levels 66–85 pmol/L) potentially behave protectively against atherosclerosis." (PMID 31958313, 2020). "Hence, in the present study we investigated hypercholesterolemic mice deficient for Nod1 as well as for Nod2 in regard to experimental atherosclerosis, lipid metabolism, insulin resistance and gut microbiota composition." (PMID 32588196, 2020). "Decreased insulin sensitivity observed in the group with high android fat may have important consequences in the development of endothelial dysfunction and atherosclerosis." (PMID 31620011, 2019). "These isomers have different activities for insulin sensitivity and atherosclerosis." (PMID 31024921, 2019). "They found similar correlates with low insulin as demonstrated here and postulated that this condition, despite high insulin sensitivity, presented a state of insufficient cell insulinization, promoting the development of atherosclerosis." (PMID 29997193, 2018). "Importantly, we described how AT ANGPTL4 modulation of lipid metabolism results in improved glucose tolerance, insulin sensitivity, and protection against the progression of atherosclerosis." (PMID 29563332, 2018). "On the contrary, FLI has proved to represent an easy screening tool to identify NAFLD in patients with cardio-metabolic risk factors where ultrasound is unavailable, which is associated with reduced insulin sensitivity, and increased risk of T2DM, atherosclerosis, and cardiovascular disease." (PMID 30551613, 2018). "Resistance to insulin's vasodilator effects is characteristic of insulin resistant and type 2 diabetic subjects, and has been shown to contribute to increased vascular resistance, defects in organ perfusion and atherosclerosis." (PMID 29628894, 2018).
atherosclerosis (continued). "In medical treatment, western medicine such as pioglitazone and metformin are used to exquisitely regulate glucose and lipid metabolism by increasing the sensitivity of insulin, which precisely control blood glucose concentration and play an anti-atherosclerosis characteristics." (PMID 30521536, 2018). "This raised the hypothesis that a direct effect from insulin on atherosclerosis or insulin-promoted medial hypertrophy may be involved." (PMID 29590246, 2018). "Based upon a previous review, insulin may mediate the association between SHBG production and atherosclerosis." (PMID 29213285, 2017). "As the level of DCN-2 was very high in T1DM individuals, it could predict that DCN-2 induced impairment of systemic NO- synthesis and insulin-synthesis might play an essential role in the development of atherosclerosis in T1DM patients." (PMID 28811499, 2017). "Previously, we and other groups have demonstrated that Cpn is effective to ameliorate metabolic disorders, such as decreasing blood lipids, improving insulin resistance and alleviating chronic inflammation, which marks Cpn as a potential therapeutic agent for atherosclerosis." (PMID 29212261, 2017). "Given the importance of myeloid cells, particularly macrophages, in the pathogenesis of both atherosclerosis and insulin signaling, we sought to determine if PTP1B deletion in these cells would have beneficial protective effects against atherosclerosis development." (PMID 28752048, 2017). "Given there is increasing evidence implicating defective insulin signalling as a major contributor to the pathogenesis of atherosclerosis, we hypothesized that PTP1B inhibition should have beneficial protective effects." (PMID 28899902, 2017). "Our data reveal a new mechanism and provide new evidence for insulin promoting atherosclerosis." (PMID 27832775, 2016). "In this study, we propose and test the hypothesis that high insulin levels can induce ER-α methylation and reduce ER-α expression, ultimately resulting in atherosclerosis." (PMID 27832775, 2016). "The administration of insulin to apo E-deleted animals could also inhibit atherogenesis, suggesting the potential anti-atherosclerosis effects of insulin." (PMID 27553774, 2016). "Our results showed that insulin can induce the formation of atherosclerosis." (PMID 27832775, 2016). "This study investigate the effects of insulin and estrogen receptor α (ER-α) in atherosclerosis." (PMID 27832775, 2016). "For example, insulin signaling in ECs modulates NO production by endothelial NO synthase (eNOS) activation and the expression of adhesion molecules, and it also attenuates the progression of atherosclerosis." (PMID 26338710, 2015). "The plasma metabolites associated with atherosclerosis in mice, namely, LDL/VLDL-cholesterol, TMAO, arginine, glucose and insulin, overlapped with those observed in humans and accounted for approximately 30 to 40% of the observed variation in atherosclerotic lesion area." (PMID 26694027, 2015). "This animal model should be useful for identifying and studying mechanisms of disease that are suggested by these associations and for testing new therapeutic approaches designed to reduce or prevent the development of severe and diffuse atherosclerosis in insulin resistant subjects." (PMID 26147990, 2015). "Overproduction of VLDL observed in insulin resistant states may lead to hypertriglyceridemia and atherosclerosis." (PMID 25875015, 2015). "Work performed by other groups suggests a somewhat different scenario where deletion of PRMT2 has a protective effect with respect to atherosclerosis as Prmt2-/- mice fed a high fat diet were resistant to weight gain and had favorable lipid profiles, glucose tolerance tests and insulin levels." (PMID 26288135, 2015). "We hypothesized that D4 receptors may also have inhibitory effect on insulin-mediated VSMCs proliferation and migration, which may inhibit the formation of atherosclerosis." (PMID 24888351, 2014).